MZF1 (myeloid zinc finger 1)
Diseases named in the same sentence as MZF1 in open-access papers (continued):
Sharing a sentence is not in itself a finding about the gene and the disease.
lung carcinoma (17 papers, 2007 to 2025). "In lung cancer, MZF1 activates the expression of the c-Myc gene (MYC) upon loss of the liver kinase B1 (LKB1)." (PMID 31963147, 2020). "A previous study has shown that FTO, as a demethylase, enhances the stability of myeloid zinc finger 1 (MZF1) mRNA in an m6A-dependent manner, promotes MZF1 expression, and inhibits lung cancer cell apoptosis." (PMID 40181982, 2025). "FTO increases the expression of myeloid zinc finger 1 (MZF1) by reducing m6A mRNA modification, and promotes lung cancer progression." (PMID 35518355, 2022). "And research pointed out that overexpressed FTO enhanced the expression of MZF1 by reducing the m6A modification level and stability of MZF1 mRNA, thereby promoting the development of lung cancer." (PMID 36523766, 2022). "Existing literature has shown that depletion of FTO effectively suppressed the proliferative and invasive potential of cells, and FTO increased MZF1 expression by demethylating MZF1 mRNA to play its oncogenic role in lung cancer." (PMID 33533172, 2021). "In lung cancer, MZF1 can upregulate the expression of NKX2-1, which in turn increases the expression of FOXM1 resulting in facilitated tumor growth and invasion." (PMID 31963147, 2020). "Overexpression of FTO in lung cancer cells could also enhance myeloid zinc finger protein 1 (MZF1) expression leading to oncogenesis." (PMID 40722726, 2025). "For example, FTO could promote the progression of lung carcinoma by releasing the m6A modification in MZF1 mRNA and strengthening its stability." (PMID 33553151, 2020). "In lung cancer, FTO downregulation increases m6A levels which then mediates downregulation of MZF1, a myeloid zinc finger protein 1 and USP7, ubiquitin-specific protease 7 due to decreased stability of their mRNA transcripts, causing an increase in lung cancer tumorigenicity." (PMID 40722726, 2025). "In lung cancer, FTO was shown to be related to poor prognosis due to its promotion of cell invasion and proliferation by controlling MZF1 expression and inhibition of lung cancer cell apoptosis." (PMID 36360287, 2022). "On the other hand, FTO was demonstrated to promote lung cancer cell proliferation by removing m6A marks from ubiquitin-specific protease 7 (USP7) and myeloid zinc finger 1 (MZF1) mRNAs in NSCLC and LUSC subtypes, respectively." (PMID 34638933, 2021). "Specifically, FTO can erase the m6A in ubiquitin specific peptidase 7 (USP7) and myeloid zinc finger 1 (MZF1) mRNAs, resulting in USP7 and MZF1 overexpression, which function as oncogenes in lung cancer." (PMID 34895230, 2021). "In lung cancer, FTO enhances the expression of MZF1 by reducing the mA level and mRNA stability of MZF1 mRNA transcription, then leading to carcinogenic function." (PMID 32547941, 2020). "Co-expression network construct indicated that some of the mostly connected mRNAs and TFs were previously reported to be dysregulated in lung cancer, including SOX2, FOXF1, PTK2B, XRCC2, AML-1a (RUNX1), GATA-2 and MZF1." (PMID 26159226, 2015). "Furthermore, FTO enhanced the expression of myeloid zinc finger 1 (MZF1) by reducing the m6A level in MZF1 mRNA and enhancing its stability, thus promoting the development of lung cancer." (PMID 32398132, 2020).
cervical carcinoma (16 papers, 2015 to 2025). A carcinoma arising from either the exocervical squamous epithelium or the endocervical glandular epithelium. "In cervical cancer SiHa cells, overexpression of MZF1 significantly suppresses invasion and migration, whereas in HeLa cells, the effects are entirely reversed." (PMID 40655141, 2025). "In another study with SiHa human cervical cancer cells, MZF1 was shown to bind the matrix metalloprotease 2 (MMP2) promoter, and a bit surprisingly to suppress its expression, and thus was reported to function as a tumor suppressor in these cells." (PMID 31963147, 2020). "In human papillomavirus infected cervical cancer, MZF1 induces the expression of another transcription factor, NKX2-1, which in turn upregulates a cancer stem cell regulator FOXM1, resulting in increased tumor growth and invasion." (PMID 31963147, 2020). "Nevertheless, MZF1 inhibited cell migration and metastasis of human cervical cancer by repressing matrix metallopeptidase 2 transcription." (PMID 32929338, 2020). "Axl expression was regulated by HPV16E6-mediated PTEN/AKT signalling pathway, and Axl promoter activity was regulated through MZF1 activation in cervical cancer, which promoted malignancy." (PMID 28720772, 2017). "The expression of Axl and MZF1 was highly associated with clinical stage and degree of HPV16/18 infection in human cervical cancer tissues." (PMID 28720772, 2017). "A recent report suggested that MZF1 induces migration, invasion, and Axl gene expression in cervical cancer cells." (PMID 28720772, 2017). "In colorectal and cervical cancer cells overexpressed MZF1 was shown to induce migration and invasion." (PMID 26697505, 2016). "MZF1 inhibits the migratory and invasive capability of cervical cancer cells through reducing MMP-2 expression." (PMID 27259238, 2016). "MZF1 promotes the progression of multiple cancers, including colorectal cancer, lung adenocarcinomas and cervical cancer." (PMID 25829251, 2015). "In cervical cancer, E6 oncoprotein augmented the expression of FoxM1 through MZF1/NKX2." (PMID 29554906, 2018). "Next, to verify whether MZF1 directly binds to Axl promoter in cervical cancer, we performed a ChIP assay using anti-MZF1 or IgG control in mock control and CE6R cells." (PMID 28720772, 2017). "Similarly to the expression of Axl, the expression levels of MZF1 were also much higher in cervical cancer than in normal tissues in tumour stage- and degree of HPV16/18 infection-dependent manners." (PMID 28720772, 2017). "In addition, the expression of Axl and MZF1 was highly correlated with clinical stage of cervical cancer and HPV16/18 infection." (PMID 28720772, 2017). "As a downstream factor of the TGF‐β1‐/ERK1/2‐/MZF1 signalling pathway, KRT17 has been shown to promote metastasis through enabling the acquisition of tumour microenvironment related cancer stem cell (CSC) properties in cervical cancer." (PMID 32537856, 2020).
prostate carcinoma (16 papers, 2009 to 2025). A carcinoma that arises from epithelial cells of the prostate gland. "MZF1 was implicated in the progression of several other cancers, including colorectal, cervical, liver, lung, and prostate cancer." (PMID 39825380, 2025). "Indeed, SCAND1 represses the co-chaperone CDC37 gene (encoding cell division control 37) by interacting with MZF1 and suppressing prostate cancer." (PMID 36982267, 2023). "Indeed, SCAND1 represses the CDC37 gene (encoding cell division control 37) by interacting with MZF1 and suppressing prostate cancer progression." (PMID 36552758, 2022). "In prostate cancer, the inhibition of MZF1 expression markedly accelerates tumor cell proliferation." (PMID 40655141, 2025). "High expression of MZF1 correlated with poor prognoses in prostate cancer and kidney cancer, whereas SCAND1 and MZF1 expression correlate with better prognoses in pancreatic cancer and stage III head and neck cancers." (PMID 36982267, 2023). "We found that heat stress induced the expression of SCAND1, SCAND2, and MZF1 bound to HSP90 gene promoter regions in prostate cancer cells." (PMID 36982267, 2023). "High expression of HSP90AA1 correlated with poorer prognoses in several cancer types, although SCAND1 and MZF1 blocked the heat shock responsiveness of HSP90AA1 in prostate cancer cells." (PMID 36982267, 2023). "MZF1 is proven to be involved in oncogenic functions in other cancers, such as colorectal carcinoma, prostate cancer, lung adenocarcinoma, and hepatocellular carcinoma." (PMID 36499054, 2022). "MiR-492 regulates MZF1 expression in prostate cancer cells, and in prostate tumors, miR-492 levels correlate reversibly with the levels of MZF1." (PMID 31963147, 2020). "As expected, depletion of MZF1 in prostate cancer cells decreases CDC37 expression and reduces their tumorigenesis." (PMID 31963147, 2020). "On the contrary, MZF1 was shown to have the opposite effect in PC3 and DU145 prostate cancer cells, where expression of MZF1 upregulated ferroportin (FPN), the only known mammalian iron exporter." (PMID 31963147, 2020). "CDC37 is a crucial molecule in prostate cancer growth through its fostering of oncogenic kinases and our data strongly indicate that the chaperone is upregulated by MZF1." (PMID 31181782, 2019). "The SCAN domain is required for the full transcriptional activity of MZF1, whereas the SCAN-only factor SCAND1 is powerfully associated with chromatin and represses the tumorigenesis of prostate cancer cells." (PMID 31181782, 2019). "GATA3 regulation happened in the early stage and the outcome of the prostate cancer at the late stage of tumor development that are related to genes MZF1, SREBF1, PRL, and DDIT3." (PMID 20025723, 2009). "Moreover, MZF1 high expression correlated with poor prognosis in patients suffering from prostate cancer." (PMID 36552758, 2022). "Moreover, myeloid zinc-finger-1 (MZF-1) inhibits prostate cancer growth by upregulating FPN1 expression." (PMID 33714956, 2021). "The role of MZF1 in prostate cancer is somewhat more complicated." (PMID 31963147, 2020). "Our data suggest a novel mechanism for prostate cancer regulation by MZF1." (PMID 31181782, 2019). "Here, we show that the SCANDs and MZF1 are stress-inducible factors and can attenuate HSP90 gene expression in prostate cancer cells." (PMID 36982267, 2023). "MZF1 has positive regulation on CDC37 gene transcription by binding the regulatory sites, while MZF1 deletion reduces CDC37 transcription and tumorigenicity of prostate cancer cells." (PMID 34732138, 2021). "We recently demonstrated that myeloid zinc finger 1 (MZF1) and SCAND1 reciprocally regulated CDC37 gene expression in prostate cancer." (PMID 32204513, 2020). "CDC37 induction is reciprocally regulated by two SCAN-type transcription factors—myeloid zinc-finger 1 (MZF1) and SCAN domain-containing protein 1 (SCAN-D1)—in prostate cancer." (PMID 31533245, 2019).
prostate carcinoma (continued). "To investigate the potential clinical significance of MZF1 regulation of CDC37, we next examined the co-expression correlation of MZF1 and CDC37 in prostate cancer patient-derived tumor samples." (PMID 31181782, 2019). "In conclusion, it was demonstrated that pro-oncogenic MZF1 and its potential antagonist SCAND1 coordinately regulate the expression of CDC37, a factor that is essential for prostate cancer tumorigenesis." (PMID 31181782, 2019). "We next examined MZF1 and CDC37 expression correlation with the prognosis of prostate cancer patients." (PMID 31181782, 2019). "We analyzed co-expression correlations of MZF1, SCAND1, and SCAND2 genes in prostate cancer." (PMID 36982267, 2023). "We next examined whether the gene expression of SCAN-TFs (MZF1, SCAND1, and SCAND2(P)) was correlated with HSF1 or HSF4 gene expression in prostate cancer specimens derived from patients." (PMID 36982267, 2023). "Additionally, MZF1 depletion repressed the transcription of CDC37 and impeded the tumorigenesis of prostate cancer, and MZF1 induced the transcriptional activities of c-Myc to mediate the progression of gliomas." (PMID 35669102, 2022). "Consistently, we have shown that overexpressing SCAND1 and MZF1 form oligomers in chromatin and bind to an MZF1-binding site in the promoter region of CDC37 gene, and hetero-oligomers of SCAND1 and MZF1 can repress CDC37 gene expression in prostate cancer." (PMID 36552758, 2022). "Consequently, increase in the expression of MZF1 inhibited tumor growth, suggesting that in respect to FPN regulation in these prostate cancer cells, MZF1 can exhibit a tumor suppressor type of function." (PMID 31963147, 2020). "MZF1 became bound to these regulatory sites and trans-activated the CDC37 gene whereas MZF1 depletion decreased CDC37 transcription and reduced the tumorigenesis of prostate cancer cells." (PMID 31181782, 2019). "We showed that MZF1 binds to sites in the CDC37 promoter and strongly activates transcription; moreover, MZF1 expression is tightly correlated with CDC37 levels in clinical prostate cancer." (PMID 31181782, 2019). "To elucidate this possibility, we asked whether tumor initiation by prostate cancer PC-3 cells could be suppressed by SCAND1 expression and by the depletion of MZF1." (PMID 31181782, 2019). "Nuclear factor erythroid 2-like 2 (NRF2) and myeloid zinc finger-1 (MZF-1) could affect cancer cells growth by regulating FPN expression in breast and prostate cancer." (PMID 29789480, 2018). "To clarify the prognostic values of MZF1 and SCAND1, we next investigated whether MZF1 and SCAND1 high or low expression correlated with survival rates of patients suffering from pancreatic, head and neck, kidney, and prostate cancers." (PMID 36552758, 2022). "High expression levels of MZF1 (p = 0.0287) and CDC37 (p = 0.0182) were correlated with poor prognosis of patients suffering from prostate cancer and showed a higher correlation than that of PSA (p = 0.154)—named after prostate-specific antigen—which is currently used for prostate cancer screening." (PMID 31181782, 2019). "Therefore, our data indicate that while MZF1 positively regulates CDC37, SCAND1 negatively regulates transcription, a finding which could be crucial in mechanisms of prostate cancer progression." (PMID 31181782, 2019).
glioma (15 papers, 2015 to 2024). A benign or malignant brain and spinal cord tumor that arises from glial cells (astrocytes, oligodendrocytes, ependymal cells). "Our data suggest that CTD treatment diminishes glioma proliferation, which is associated with the down-regulation of MZF1 and c-MYC." (PMID 36499054, 2022). "In glioma cells, Linc01060 promotes myeloid zinc finger 1 (MZF1) stabilization, enhanced c-Myc activity, and increased HIF1α levels, which in turn activate Linc01060 transcriptionally in a positive feedback loop." (PMID 39585046, 2024). "Our findings suggest that MZF1 overexpression promotes the proliferation of patient-derived glioma cells." (PMID 36499054, 2022). "To this end, we examined which Chinese medicines inhibited MZF1 expression in gliomas and prevented glioma cell proliferation." (PMID 36499054, 2022). "Nucleocytoplasmic transport has been reported to affect the translocation of MZF1 into the nucleus, inhibiting gene transcription in gliomas." (PMID 36499054, 2022). "In conclusion, MZF1, an oncogenic transcription factor, promotes glioma proliferation by inducing c-MYC expression." (PMID 36499054, 2022). "Overexpression of MZF1 in PT#3 and A172 cells induced glioma proliferation after four and seven days, respectively." (PMID 36499054, 2022). "MZF1 overexpression is proposed to contribute to the proliferation and growth of gliomas through the regulation of c-MYC." (PMID 36499054, 2022). "We observed higher expression of MZF1 in glioma cells compared with normal human astrocytes, and MZF1 is associated with worse overall survival in GBM patients." (PMID 36499054, 2022). "MZF1 overexpression in different types of cancer reportedly promotes tumor progression, especially in glioma." (PMID 36499054, 2022). "Based on the data collected in the present study, combined with bioinformatics analysis and cellular experiments, MZF1 was confirmed to act on a specific oncogenic pathway in gliomas." (PMID 36499054, 2022). "Another recent study revealed that exosomes derived from hypoxic glioma stem cells contain an elevated level of Linc01060, which supports glioma progression by regulating the MZF1/c-Myc/HIF-1α axis and is correlated with a poor clinical prognosis." (PMID 34681857, 2021). "The endogenous expression of MZF1 among different glioma cells may contribute to the genetic backgrounds, transcriptional and translational regulations, and posttranslational modifications." (PMID 36499054, 2022). "Our result shows that the proliferation of glioma cells was enhanced by MZF1 overexpression." (PMID 36499054, 2022). "Our combined data showed that CTD inhibited the MZF1/c-MYC axis in glioma cell proliferation." (PMID 36499054, 2022). "According to our results, MZF1 plays an oncogenic role in promoting glioma cell proliferation." (PMID 36499054, 2022). "We also examined the effect of CTD, which inhibits MZF1, on the prevention of glioma proliferation." (PMID 36499054, 2022). "Another study with glioma cell lines indicates that overexpression of miR-101 leads to a decrease in MZF1 expression, without going further into detail in regard to its potential binding sites in MZF1." (PMID 31963147, 2020). "Therefore, MZF1 and c-Myc indeed contribute to glioma tumorigenesis." (PMID 36499054, 2022). "We examined whether CTD treatment reduced MZF1 expression in glioma cells." (PMID 36499054, 2022). "Therefore, we overexpressed MZF1 in gliomas to investigate cell proliferation." (PMID 36499054, 2022). "Next, we examined whether CTD inhibited glioma proliferation by inhibiting MZF1 expression." (PMID 36499054, 2022). "MZF1 reportedly interacts with c-MYC to promote cancer progression in colorectal carcinoma, lung adenocarcinoma, and glioma." (PMID 36499054, 2022).
glioma (continued). "Previous research demonstrated that long noncoding RNA 01060 (lncRNA01060) increases MZF1 translocation into the nucleus and promotes MZF1-regulated c-Myc, HK2, and PGK1 transcription in glioma, facilitating aerobic glycolysis and inducing tumor progression." (PMID 36499054, 2022). "In this study, we found that the expression of MZF1 was higher in GBM tissues than in adjacent normal tissues and low-grade gliomas." (PMID 36499054, 2022). "The results of our study demonstrate that CTD treatment is markedly more effective than NCTD treatment in inhibiting glioma proliferation and that CTD can effectively reduce the expression of MZF1." (PMID 36499054, 2022). "miR-101 epigenetically suppresses the expression of LIM domain only 3 (LMO3) by inhibiting the binding of Upstream stimulatory factor 1 (USF) and Myeloid Zinc Finger 1 (MZF1) to the LMO3 promoter and induces cell apoptosis in U251 glioma cells." (PMID 30583549, 2018). "In this study, we found that the endogenous MZF1 protein levels in glioma cells (PT#3 and A172, but not U87MG) were markedly higher than that in primary astrocytes." (PMID 36499054, 2022). "Using bioinformatics analysis, we found that MZF1 expression was higher in glioma tissues than in non-tumor and low-grade glioma tissues." (PMID 36499054, 2022). "In glioma cell lines, MZF1 binds directly to the LIM-only protein 3 (LMO3) promoter and induces the expression of LMO3, which is a transcriptional co-activator that can act as an oncogene in glioma, one of the most aggressive and most common tumors of the central nervous system." (PMID 31963147, 2020). "There are currently no data showing the function of MZF1 in gliomas." (PMID 25829251, 2015).